CACNA1D (calcium voltage-gated channel subunit alpha1 D)
Diseases named in the same sentence as CACNA1D in open-access papers (continued):
Sharing a sentence is not in itself a finding about the gene and the disease.
prostate carcinoma (17 papers, 2014 to 2025). A carcinoma that arises from epithelial cells of the prostate gland. "CACNA1D, encoding CaV1.3 ion channels is upregulated in prostate cancer." (PMID 36949059, 2023). "CACNA1D is believed to regulate cell firing, and is highly associated with prostate cancer." (PMID 34566889, 2021). "In addition, up-regulation of CACNA1D expression has been linked to prostate cancer progression." (PMID 26010603, 2015). "In prostate cancer, CACNA1D mRNA and protein levels are significantly upregulated, and its overexpression correlates with an aggressive tumor phenotype." (PMID 41155636, 2025). "Specifically, a previous study report CACNA1D overexpression and activate voltage-gated calcium channels in prostate cancer during androgen deprivation." (PMID 39175079, 2024). "Genes in NK cells (i.e., BCL11B for T-ALL, MAP3K7IP2 for prostate cancer) and in monocytes (i.e., LCK and BCL11B for T-ALL, PDCD1LG2 for Hodgkin’s lymphoma, PRDM16 for AML, CACNA1D for prostate cancer) were found significant in our meta-EWAS." (PMID 38466776, 2024). "Compared to normal prostate cells, the hormone-responsive and hormone-resistant prostate cancer cells overexpress CACNA1-D, TRPM-7, and TRPV-6." (PMID 38131032, 2023). "An epigenomic-profiling study of prostate cancer tumors noted that CACNA1D was among the top-ten-ranked differentially-methylated (hypomethylated) genes in tissues with ERG fusion, compared to those without." (PMID 36046118, 2021). "In a study of radical prostatectomy patients, CACNA1D-expression was correlated with a higher Gleason score (a grading system for prostate cancer) and biochemical recurrence." (PMID 36046118, 2021). "Relevant bioinformatics analysis also confirmed that CACNA1D was highly expressed in prostate cancer, breast cancer, colorectal cancer, gastric cancer, lung cancer, uterine cancer, and other cancers." (PMID 34566889, 2021). "At last, the four genes, DTNA, PRR11, TMEM178B, and CACNA1D, were mainly related to gastric cancer or prostate cancer." (PMID 32964043, 2020). "There is a compelling body of evidence that CaV1.3 (CACNA1D) is overexpressed in prostate cancer at the gene and protein levels." (PMID 27342111, 2016). "Nevertheless, some studies relate its expression- and methylation-level to prostate cancer, indicating CACNA1D as a possible regulator of prostate cancer aggressiveness, or refer it to CNS disorders, diabetes or calcium level within the vessels." (PMID 27716384, 2016). "A study of CACNA1D in prostate cancer in the ONCOMINE database revealed its significant overexpression in cancer tissues compared with normal prostate, consistent with findings of CACNAID mRNA and CaV1.3 protein expression in prostate cancer cell lines." (PMID 27342111, 2016). "Prostate cancers such as prostate carcinoma, intraepithelial neoplasia, and adenocarcinoma all showed dramatic overexpression of CACNA1D relative to normal tissues." (PMID 26147197, 2015). "CACNA1D is believed to regulate cell firing and has a high correlation with prostate cancer; however, its expression in other cancer types is still largely unstudied." (PMID 26147197, 2015). "A particularly novel finding was that CACNA1D was highly expressed in prostate cancer but also in breast, colorectal, bladder, gastric, lung, brain, uterine, and esophageal tumors." (PMID 26147197, 2015). "Increasingly it is being realized that ligand independent activation of AR is regulated in CACNA1D overexpressing prostate cancer cells." (PMID 24739220, 2014). "ERG target genes such as calcium channel, voltage-dependent, L type, α-1D subunit (CACNA1D) were significantly upregulated in TMPRSS2-ERG positive prostate cancer cells." (PMID 24739220, 2014). "It has recently been documented that another antihypertensive agent and a CCB, nifedipine, could suppress prostate cancer progression by modulating CACNA1D expression." (PMID 39958978, 2025).
prostate carcinoma (continued). "Stratification of patient data, e.g., in prostate cancer by the presence of the TMPRS2-ERG fusion status where it is known that CACNA1D is highly overexpressed, may show benefits of CCB use prior to development of aggressive disease." (PMID 27342111, 2016). "Compared to nontumorigenic cells, the hormone-dependent cells overexpressed TRPM-7 and TRPV-6 and the hormone-resistant cells overexpressed CACNA1-D, TRPM-7, and TRPV-6, supporting the role of calcium channels in prostate cancer." (PMID 38131032, 2023). "CACNA1D and CaV1.3 protein are overexpressed in prostate tumours and CACNA1D was overexpressed in androgen-sensitive prostate cancer cells." (PMID 36949059, 2023). "An analysis of the Oncomine dataset revealed that CACNA1D-expression was significantly higher in prostate cancers with the ERG-gene fusion, compared with the cases without this gene fusion." (PMID 36046118, 2021).
epilepsy (16 papers, 2016 to 2025). A brain disorder characterized by episodes of abnormally increased neuronal discharge resulting in transient episodes of sensory or motor neurological dysfunction, or psychic dysfunction. "Another gain-of-function CACNA1D variant (V401L) was also linked to autism spectrum disorder and epilepsy." (PMID 40564095, 2025). "Dysregulation of CACNA1D has been implicated in various neurological disorders, including epilepsy and autism spectrum disorders." (PMID 38785745, 2024). "Our findings strengthen the evidence of CACNA1D not only as a novel autism risk gene but also as a risk gene for epilepsy." (PMID 28472301, 2017). "Taken together, our data strongly support CACNA1D as a gene contributing to the risk for a number of psychiatric and neurological manifestations including intellectual disability, epilepsy, neuromuscular symptoms and ASD." (PMID 28472301, 2017). "Recent findings provide evidence that human mutations in the CACNA1D gene can confer risk for the development of neuropsychiatric disease and perhaps also epilepsy." (PMID 26842699, 2016). "Additionally, there are also variants in genes related to epilepsy, such as CACNA1D (AUT142), CHD1 (AUT183), KMT2E (AUT184), and CHD2 (AUT195)." (PMID 38003033, 2023). "Of note, genetic variation in CACNA1D was also associated with epilepsy." (PMID 36430690, 2022). "Moreover, we strengthen the evidence that CACNA1D mutations are also associated with epilepsy and epilepsy with neuromuscular symptoms as described in PASNA patients." (PMID 28472301, 2017). "However, this neurological phenotype also prompted us to screen the literature for additional CACNA1D variants reported in epilepsy." (PMID 26842699, 2016). "Moreover, administration of NPSs expressing normal Cacna1d may prove to be therapeutically potent in ameliorating the detrimental effects of mutated LTCCs associated with epilepsy." (PMID 33815100, 2021). "CACNA1D, which encodes one of the L-type calcium channels is similarly associated with (SFARI Category 2) ASD, ID and epilepsy." (PMID 39849619, 2025). "Exome sequencing has identified various mutations of CACNA1D in ASD, epilepsy developmental delay endocrine issues, CACNA2D1 in epilepsy and intellectual disability and CACNB2 mutations in ASD." (PMID 33338084, 2020). "Exome sequencing has identified various CACNA1D mutations (encoding Cav1.3) in ASD, epilepsy, and developmental delay." (PMID 31893021, 2019). "Here we report the discovery and characterization of a third de novo missense mutation in CACNA1D (V401L) in a patient with ASD and epilepsy." (PMID 28472301, 2017). "CACNA1D and CACNA1G encode subunits of voltage-gated calcium channels expressed in neurons, and variants in both genes have been implicated in neurodevelopmental disorders such as autism spectrum disorder (ASD) and epilepsy." (PMID 41442065, 2025). "Since the LQTS phenotype was not present in the index family, we continued with a further characterization of the heterozygous variant NM_000720.3:c.2789G>A in the CACNA1D gene as a possible causative gene variant for the clinically combined phenotype of SND and epilepsy." (PMID 36430690, 2022). "Interestingly enough, gain-of-function mutations of CACNA1D (which is the gene coding for Cav1.3) but not of CACNA1C (coding for Cav1.2) have been linked to epilepsy." (PMID 30699993, 2019). "This review delves into the significance of the CACNA genes, including CACNA1A, CACNA1B, CACNA1C, CACNA1D, CACNA1E, CACNA1G, and CACNA1H, in the pathogenesis of conditions such as migraine, epilepsy, cerebellar ataxia, dystonia, and cerebellar atrophy." (PMID 38785745, 2024). "Here, no additional putative pathogenic variants were detected, indicating that CACNA1D variants might be present in rare and complex (SND + epilepsy), but not isolated phenotypes of SND." (PMID 36430690, 2022). "In addition to Cacna1d, altered expression of gene NRXN1 may also play a role in epilepsy." (PMID 33815100, 2021).
Hypertension (15 papers, 2015 to 2025). The presence of chronic increased pressure in the systemic arterial system. "Given that isradipine is approved for the therapy of hypertension, calcium channel blocker therapy could be a treatment option in patients with PA due to somatic CACNA1D mutations." (PMID 37698934, 2023). "While somatic mutations identified in aldosterone producing adenomas (APAs) underlie treatment-resistant hypertension, germline CACNA1D mutations are associated with a neurodevelopmental disorder characterized by a wide symptomatic spectrum, including autism spectrum disorder." (PMID 30465465, 2018). "For instance, mutations in the CACNA1D (primary aldosteronism) and NR3C2 (Geller syndrome) genes are known causes of monogenic hypertension." (PMID 37059828, 2023). "The finding that the gene collapsing analyses in essential hypertension identified variation in genes (PKD1, PKD2, COL4A4, UMOD, CACNA1D, and NR3C2) that are possible causes of undiagnosed secondary hypertension is worthy a special comment." (PMID 37059828, 2023). "The genetic polymorphisms of the CACNA1D, HLAB, CYP11B1, and LSP1 gene regions showed significant association with hypertension." (PMID 36233190, 2022). "An example of a known drug targeting an MXE gene is a voltage gated Calcium channel CACNA1D which is targeted by a number of drugs for hypertension such as Amlodipine (DrugBank:DB00381)." (PMID 33651795, 2021). "The CACNB2 and CACNA1D genes have shown network with coronary diseases, hypertension, diabetes, BPD and depression." (PMID 28117839, 2017). "As such, genetic variation in CACNA1D may increase the odds of developing hypertension, a condition that contributes to the occurrence of renal dysfunction after heart transplantation and which is exacerbated by CNI use." (PMID 33868389, 2021). "Another intronic variant in CACNA1D, rs9810888, has previously been associated with the presence of hypertension in non-transplanted adults." (PMID 33868389, 2021). "From a cohort of more than 1500 unrelated subjects referred for evaluation of genetic forms of hypertension, we identified 40 subjects diagnosed with hypertension and PA by age 10 years in whom disease-causing mutations in CYP11B2, KCNJ5, and CACNA1D were excluded." (PMID 25907736, 2015). "While germline mutations in KCNJ5 and CACNA1D were discovered following the initial identification of their somatic mutations in APAs, the discovery of the recurrent CACNA1H mutation relied entirely on brute force sequencing of patients with early severe aldosteronism and hypertension." (PMID 25907736, 2015).
autism (14 papers, 2015 to 2026). Persistent deficits in social interaction and communication and interaction as well as a markedly restricted repertoire of activity and interest as well as repetitive patterns of behavior. "This feature appears to be more prominent in mice homozygous for a Cacna1d mutation associated with autism in humans, demonstrating that the spectrum from disorder to disease associated with different mutations in humans is well reflected in mouse models." (PMID 37698934, 2023). "Our findings strengthen the evidence for CACNA1D as a novel candidate autism risk gene and encourage experimental therapy with available channel-blockers for this mutation." (PMID 28472301, 2017). "We screened WES data in patients with sporadic autism for other CACNA1D de novo mutations and identified p.G407R in another patient, for which we also demonstrate a pronounced gain-of-function." (PMID 25620733, 2015). "In addition, germline mutations in CACNA1D have been linked to neurodevelopmental syndromes including epileptic seizures, autism, intellectual disability and primary hyperaldosteronism." (PMID 36430690, 2022). "Persons with certain single nucleotide polymorphisms (SNPs) in the CACNA1D gene (encoding voltage-gated calcium channel subunit alpha 1-D) have increased risk of developing neuropsychiatric disorders such as bipolar, schizophrenia and autism." (PMID 33057948, 2021). "De novo variations in Cav1.3 subunit (CACNA1D) were identified in a cohort of patients affected with autism along with intellectual disability." (PMID 29934975, 2018). "A whole-exome sequencing study identified a de novo mutation, p.A749G, in Cav1.3 α1-subunits (CACNA1D), the second main LTCC in the brain, as 1 of 62 high risk–conferring mutations in a cohort of patients with autism and intellectual disability." (PMID 25620733, 2015). "This pattern was consistent with those of other autism risk genes, such as GRIN2B (correlation coefficient (r) = 0.65, p < 2.2e-16), SCN2A (r = 0.64, p < 2.2e-16), and CACNA1D (r = 0.51, p < 2.2e-16), suggesting a coordinated increase during the fetal third trimester." (PMID 39363111, 2024). "Moreover, a whole exome resequencing study identified rare de novo alleles of CACNA1D and CACNA1E as "top de novo risk mutations" for autism." (PMID 26566276, 2015).
autism spectrum disorder (13 papers, 2015 to 2025). A spectrum of developmental disorders that includes autism, and Asperger syndrome. "Here we provide proof of the disease-causing nature of such gating-modifying CACNA1D variants using mice (Cav1.3AG) containing the A749G variant reported de novo in a patient with autism spectrum disorder (ASD) and intellectual impairment." (PMID 37698939, 2023). "Mutations in Cacna1d exon 8a have been implicated in autism spectrum disorder, and alternative splicing of exon 8 may contribute to channel voltage dependency differences." (PMID 38318533, 2024). "Our data strongly support CACNA1D as a recurrent risk gene for autism spectrum disorder (ASD)." (PMID 25620733, 2015). "De novo missense mutations in the gene of their pore-forming α1-subunit (CACNA1D) induce severe gating defects which lead to autism spectrum disorder and a more severe neurological disorder with and without endocrine symptoms." (PMID 38553610, 2024).
breast carcinoma (13 papers, 2015 to 2025). "Downregulation of CACNA1D inhibits filopodia formation and suppresses the invasive capacity of breast cancer cells." (PMID 41155636, 2025). "We performed expression analyses of five genes (GBP2, GPR171, DIRAS3, RAC2, CACNA1D) obtained from the LASSO model to observe their expressions in primary breast cancer and metastatic breast cancer." (PMID 36212434, 2022). "Some of these biomarkers, including E2F8, TPX2 and CACNA1D, have been independently confirmed as tumourigenic or tumour-suppressive in breast cancer, and can thus point towards novel targets for treatment." (PMID 34131308, 2021). "Our bioinformatics analysis verified that CACNA1D was highly expressed in most types of cancer, including prostate and breast cancer." (PMID 26147197, 2015). "This bioinformatics analysis revealed that different subtypes of VGCCs (CACNA1C, CACNA1D, CACNA1B, CACNA1G, and CACNA1I) are implicated in the development and progression of diverse types of cancer and show dramatic up-regulation in breast cancer." (PMID 26147197, 2015). "In particular, CACNA1D, which localizes to filopodia tips and contributes to cancer cell invasion in vitro (shown in this study), was found to be expressed in patient samples in all major breast cancer subtypes." (PMID 27910855, 2016). "Therefore, L-type calcium channels, in particular CACNA1S and CACNA1D are expressed in breast cancer and contribute to filopodia formation and cancer cell invasion." (PMID 27910855, 2016). "In addition, CACNA1D protein expression could be detected in all major breast cancer subtypes (cancer type, positive expression; luminal, 3/6; triple-negative, 7/8; Her2-positive, 4/4; healthy breast, 0/1) from a set of breast carcinoma patient samples." (PMID 27910855, 2016). "For instance, breast cancer showed dramatic upregulation of CACNA1C, CACNA1D, CACNA1B, CACNA1G, and CACNA1I." (PMID 26147197, 2015). "In our study, CACNA1D expression was lower in breast cancer samples of nonobese patients than obese patients." (PMID 34566889, 2021). "Furthermore, while all four L-type calcium channel α1 subunits are expressed at low levels in both healthy breast and breast carcinoma samples (IST Online), CACNA1D is the most commonly overexpressed α1 subunit in breast carcinoma while CACNA1F is often downregulated." (PMID 27910855, 2016). "Of the L-type calcium channel α1 subunits, expression of CACNA1D, CACNA1S, but not CACNA1C, was detected in MDA-MB-231 cells at the mRNA level (CACNA1F was not tested as it appeared to be often downregulated in breast cancer clinical samples)." (PMID 27910855, 2016).
Intellectual disability (12 papers, 2015 to 2023). "In support of these findings, missense variants in CACNA1C and CACNA1D are associated with syndromic intellectual disability and common variants are associated with psychiatric disorders." (PMID 36824672, 2023). "Similar to Cav1.2, missense coding genetic variants in CACNA1D (Cav1.3) have been linked to ASD and intellectual disability." (PMID 36803254, 2023). "Similarly, SNPs in CACNA1D have been linked to BD, SCZ, ASD, and intellectual disability (ID)." (PMID 36803254, 2023).
depression (10 papers, 2015 to 2024). "Furthermore, whole-exome sequencing revealed variants in the CACNA1D coding region to be linked to ASD, depression, anxiety, fear and seizures." (PMID 33057948, 2021).
endometrial cancer (10 papers, 2016 to 2025). Primary or metastatic malignant neoplasm involving the endometrium (mucous membrane that lines the endometrial cavity). "Silencing the CACNA1D gene (encoding α1D) disrupts Ca2+ homeostasis and impairs the migration of colorectal cancer and endometrial carcinoma cells." (PMID 41155636, 2025). "Specifically, upregulation of CACNA1D was associated with increased proliferation and migration in endometrial carcinoma tissue." (PMID 36046118, 2021). "Likewise, CaV1.3 encoded by the human CACNA1D gene is overexpressed in prostate and endometrial cancers." (PMID 32575381, 2020).